STAT1 (signal transducer and activator of transcription 1)
Diseases named in the same sentence as STAT1 in open-access papers (continued):
Sharing a sentence is not in itself a finding about the gene and the disease.
ZIKV infection (29 papers, 2017 to 2026). "Further studies identified that the cleavage site is the aspartic acid 694, and the D694A mutation rendered STAT1 resistant to ZIKV infection-induced cleavage." (PMID 38018976, 2024). "The inhibition of AXL during a ZIKV infection in Sertoli cells causes: (i) the inactivation of STAT1, (ii) the reduction of SOCS-1, and (iii) an interferon-induced antiviral gene (ISG) expression that decreases the viral replication." (PMID 36557673, 2022). "In the current study, we showed that mice with STAT1 knockout (Stat1-/-) were highly susceptible to ZIKV infection." (PMID 29668683, 2018). "The double knockout mice were equally susceptible as Stat1-/-mice to a ZIKV infection suggesting that the upregulation of these proinflammatory cytokines might not be critical in ZIKV-induced pathology and mortality." (PMID 29668683, 2018). "ZIKV infection significantly reduced the protein levels of STAT1 in the absence or presence of IFN treatment at 48 and 72 h post-infection." (PMID 38018976, 2024). "In the Huh7.5-GFP control cell lines, ZIKV infection at an MOI of 5 induced cleavage of the endogenous STAT1 and the accumulation of the 81 kDa STAT1." (PMID 38018976, 2024). "By regulating STAT1 abundance in response to ZIKV infection, downstream effects following IFN-β (and/or IFN-γ) induction of the pathway would impact ISG expression and functions." (PMID 39212382, 2024). "In this study, by using an infectious clone of ZIKV MR766 (C7) as a tool, we found that ZIKV infection triggered caspase-dependent cleavage of STAT1 at aspartic acid 694 during late infection." (PMID 38018976, 2024). "Herein, we found that ZIKV infection triggered caspase-dependent cleavage of STAT1 at the aspartic acid 694 during late infection, whereas murine STAT1 (mSTAT1) was resistant to cleavage." (PMID 38018976, 2024). "In contrast, mSTAT1-D695G was readily cleaved in the ZIKV-infected cells, suggesting that D695 is the determinant amino acid for murine STAT1 cleavage upon ZIKV infection." (PMID 38018976, 2024). "Strikingly, ZIKV infection resulted in the production of a new 81 kDa STAT1 species from 2 days post-infection." (PMID 38018976, 2024). "We first examined the effect of ZIKV infection on the protein levels of STAT1 and phosphorylated STAT1 (pSTAT1)." (PMID 38018976, 2024). "Murine STAT1 (mSTAT1) was resistant to ZIKV infection-induced cleavage and STAT1 knockout in mouse embryonic fibroblast NIH3T3 cells dramatically augmented ZIKV infection." (PMID 38018976, 2024). "In this study, we used infectious clones of ZIKV MR766 as tools and found that ZIKV infection triggered caspase-dependent cleavage of STAT1 during late infection." (PMID 38018976, 2024). "We further knocked out STAT1 in the mouse embryonic fibroblast NIH3T3 cells, and STAT1 knockout dramatically augmented ZIKV infection, suggesting a STAT1-mediated viral restriction." (PMID 38018976, 2024). "Molecules involved in type I IFN signaling are also increased by ZIKV infection, such as STAT1, DDX60L, DDX60, DDX58, STAT2, and IRF7." (PMID 36142200, 2022). "MAPK1 dysregulation induces chorio-retinal atrophy and optic nerve abnormalities in ZIKV infections and STAT1/2 is involved in antiviral responses; in addition, ZIKV NS5 protein-mediated STAT2 degradation modulates type I and III interferon responses." (PMID 36680137, 2022). "The overactivated innate immune responses in hNS/PCs during early stage infection, particularly the robust induction of STAT1 expression and activation led us to investigate the role of STAT1 in neurogenesis impairment after ZIKV infection." (PMID 33657175, 2021). "In our study, the transcription level of STAT1 was robustly increased by more than 10-fold after ZIKV infection, while others only altered moderately or mildly." (PMID 33657175, 2021). "Another recent study observed C25H induction following Zika virus infection via type-I interferon independent STAT1-dependent pathway." (PMID 34551004, 2021).
ZIKV infection (continued). "In cells stably expressing TLR3, activation of IRF3 was not substantially affected; however, we observed an ∼50% reduction of STAT1 phosphorylation during ZIKV infection." (PMID 33658344, 2021). "Particularly, the transcription level of STAT1 was increased by more than 10-fold after ZIKV infection in the early stage." (PMID 33657175, 2021). "In A549 cells and human DCs, ZIKV infection diminished the pools of endogenous phosphorylated STAT1 and STAT2 (p-STAT1/2), at residues Tyr-701 and Tyr-689, respectively, in the presence and absence of exogenous IFN treatment." (PMID 31652496, 2019). "We further show here that ZIKV infection of SC induces expression and phosphorylation of STAT1, an important molecule involved in IFNAR and Axl-IFNAR signaling." (PMID 31311882, 2019). "ZIKV infection induced strong upregulation of genes associated with IFN signaling such as IFNα, IFNβ, STAT1, and STAT2." (PMID 30781519, 2019). "In contrast, ZIKV-infected Ifnar-/- mice showed much less weight loss and only had a 20% mortality rate (p = 0.0199) when challenged with 4x104 pfu/mouse compared to the Stat1-/- mice with the same ZIKV infection dose." (PMID 29668683, 2018). "Earlier work suggested that ZIKV NS5 targets STAT2 for degradation 19, 28 and that ZIKV infection blocks STAT1 phosphorylation." (PMID 29572905, 2018). "To develop new tools for ZIKV research, we determined that a genetically modified mouse strain, Stat1-/-, was highly sensitive to ZIKV infection." (PMID 29668683, 2018). "We next determined the threshold of ZIKV infection in the mosquito by allowing uninfected mosquitoes to take blood meals from Stat1-/- mice exposed to various infection doses." (PMID 29668683, 2018). "We found that ZIKV infection induced weak activation of Jak1 and STAT1, and reduced the phosphorylation of Jak1 and STAT1 after IFNβ stimulation." (PMID 28373913, 2017). "Taken together, these data demonstrate that complementation of murine cleavable STAT1 variant elicits comparable antiviral signaling as the cleave-resistant murine wild-type STAT1, which suggests that ZIKV infection-induced STAT1 cleavage is dispensable for antiviral evasion in murine cells." (PMID 38018976, 2024). "Murine STAT1 was resistant to ZIKV infection-induced cleavage." (PMID 38018976, 2024). "To explore whether ZIKV infection affects the expression of STAT1 in a similar manner, we used the Huh7.5 cell line that stably expresses an unstable GFP (GFPu), which is used as a monitor of proteasome activity." (PMID 38018976, 2024). "STAT1 knockout in mouse embryonic fibroblast NIH3T3 cells dramatically augmented ZIKV infection." (PMID 38018976, 2024). "Herein, we extended our study to explore the effect of ZIKV infection on STAT1." (PMID 38018976, 2024). "Wild-type murine STAT1 (mSTAT1), as expected, was resistant to ZIKV infection-induced cleavage." (PMID 38018976, 2024). "However, STAT2 translocation, phosphorylation and total protein levels were more potently reduced by ZIKV infection compared to STAT1." (PMID 36897927, 2023). "ZIKV infection of microglia up-regulated STAT1/p-STAT1 and STAT2/p-STAT2 expression." (PMID 35522620, 2022). "During a ZIKV infection in Sertoli cells, the transcription factor STAT1, an important molecule in the AXL-IFNAR signaling pathway, is activated; promoting the expression of suppressor of cytokine signaling 1 (SOCS1) and the restriction of the interferon response." (PMID 36557673, 2022). "These included MX1, IFIT1, ISG15, SAMHD1, IFIT3, and STAT1, all of which have been shown to be similarly upregulated by ZIKV infection in other human cell types, including fibroblasts and pluripotent stem cell (iPSC)-derived neural progenitor cells (NPC), as also demonstrated by LC-MS/MS analysis." (PMID 34079533, 2021).
ZIKV infection (continued). "For example, while several groups have shown reduced STAT1 phosphorylation during ZIKV infection, it is still unknown which ZIKV proteins or potential cellular factors are involved in this antagonistic approach." (PMID 31652496, 2019). "Taken together, Stat1-/- mice were more sensitive to ZIKV infection than Ifnar-/-." (PMID 29668683, 2018). "In the present study, Stat1-/- mice were used to establish a ZIKV infection model." (PMID 29668683, 2018). "In contrast to Stat1-/- mice, wild-type (WT) mice were resistant to a ZIKV infection." (PMID 29668683, 2018). "However, the percentage of CD11c+ DCs was drastically increased in Ifnar-/- mice at 60 h post-ZIKV infection compared to those in infected Stat1-/- mice (p<0.0001)." (PMID 29668683, 2018). "With the different outcome of ZIKV infection in Ifnar-/- and Stat1-/- mice, cDC and macrophage activation might be the key components of protective immune responses." (PMID 29668683, 2018). "Analysis of the ratio of total and phosphorylated STAT1 by densitometry showed that NS5 expression prevented STAT1 phosphorylation suggesting that NS5 is the viral protein blocking STAT1 phosphorylation during ZIKV infection." (PMID 29572905, 2018). "Additionally, ZIKV infection has been suggested to prevent STAT1 and STAT2 phosphorylation." (PMID 29572905, 2018). "In addition, ZIKV infection also reduced IFNβ-induced nuclear translocation of STAT1." (PMID 28373913, 2017). "Interestingly, while ZIKV infection alone did induce low levels of STAT1 and STAT2 phosphorylation, in most conditions, there was a notable decrease in phosphorylation at MOIs of 1 as compared to MOIs of 0.1, a finding most profound with the African lineage viruses." (PMID 28152048, 2017). "The mouse is resistant to ZIKV infection, whereas STAT1 knockout mouse is highly sensitive to ZIKV, suggesting that STAT1 signaling plays an important role in restricting ZIKV infection." (PMID 38018976, 2024). "A recent study on human Sertoli cells showed that Zika virus infection can counteract BMP6 signaling, and that BMP6 induces phosphorylation of IRF3 and STAT1, and increases expression of IFNβ and some ISGs." (PMID 38308064, 2024). "The oncoprotein PIM1 kinase was revealed to inhibit the cellular type I IFN signaling pathway by vaguely regulating the phosphorylation of STAT1 or STAT2, which therefore promoted viral replication during ZIKV infection." (PMID 39679197, 2024). "Among the ZIKV dysregulated cellular functions at 48 h post ZIKV infection, which was the timepoint with the largest number of dysregulated proteins, MAPK1 was predicted to be activated and STAT1/2 inhibited." (PMID 36680137, 2022). "In the present study, ZIKV infection was shown to suppress type I IFN-mediated response and inhibited phosphorylation of STAT1 and STAT2 in moDCs, which is in line with previous findings." (PMID 33979266, 2021). "Indeed, ZIKV infection under conditions of antibody-mediated sequestration of IL-6, which was released from the cells into the culture supernatant, resulted in ∼3-fold-enhanced STAT1 phosphorylation (top blot), whereas STAT3 phosphorylation and SOCS3 expression were significantly reduced." (PMID 33658344, 2021). "We found that ZIKV infection (MOI of 10) induced phosphorylation of STAT1 and that R428 treatment reduced levels of p-STAT1 in both mock-infected and infected SC." (PMID 31311882, 2019). "Recent studies have shown that ZIKV can interfere with interferon-induced responses: ZIKV infection inhibits STAT1 and STAT2 phosphorylation, and especially ZIKV NS5 protein inhibits STAT1 phosphorylation and induces the proteasomal degradation of STAT2." (PMID 31690057, 2019). "Therefore, to investigate whether Axl kinase augments ZIKV infection of human SC by negatively regulating antiviral response, we first evaluated the effect of R428 treatment on protein levels of STAT1/p-STAT1 (phosphorylated STAT1), SOCS1, and SOCS3." (PMID 31311882, 2019).
ZIKV infection (continued). "Upon ZIKV infection, SSC+ myeloid cells were increased in both Stat1-/- and Ifnar-/- mice compared to those in uninfected Stat1-/- mice (p<0.0001)." (PMID 29668683, 2018). "Because mice are naturally immune to a ZIKV infection, mouse strains defective in antiviral immune pathways such as AG129, Ifnar-/-, Stat1-/-, Stat2-/- and Irf3-/-Irf5-/-Irf7-/- triple knock out mice have been used in ZIKV pathogenesis research." (PMID 29668683, 2018). "Taken together, these results indicate that ZIKV infection reduces the protein levels of STAT1 but not the phosphorylated STAT1." (PMID 38018976, 2024). "After normalization (p-STAT1/total STAT1), the data showed that ZIKV infection did not affect the STAT1 phosphorylation." (PMID 38018976, 2024). "Our observation of increased STAT3 phosphorylation upon ZIKV infection in the presence of TLR3 and the downregulation of STAT1 signaling is in agreement with the well-established interplay between these two transcription factors (recently reviewed in reference 69)." (PMID 33658344, 2021). "In contrast, ZIKV infection in MDMs did not counteract the phosphorylation of STAT1 or STAT2 stimulated by IFN-α treatment." (PMID 33979266, 2021). "However, host immune responses are weakened due to the degradation of STAT1 and STAT2 transcription factors that initiate the transcription of ISGs by NS2A during ZIKV infection." (PMID 34745057, 2021). "Our study emphasizes the involvement of both STAT1 and RACK1 in the immune response elicited by the ZIKV infection, suggesting ZIKV might employ a similar approach to suppress the host immune response." (PMID 32753727, 2020). "Splenocytes were isolated from WT, Stat1-/- and Ifnar-/- mice without or with ZIKV infection (60 h post-infection, 4x104 pfu/mouse) and analyzed by flow cytometry with various cell lineage markers." (PMID 29668683, 2018). "Stat1-/- mice were more sensitive than Ifnar-/- mice to ZIKV infection without any discernable gender or age differences." (PMID 29668683, 2018). "In this study, we first found that ZIKV infection did not affect STAT1 phosphorylation." (PMID 38018976, 2024). "Therefore, we tested a STAT1 inhibitor, Fludarabine (FAMP), in K048 hNS/PCs after ZIKV infection, to see whether inhibiting the overactivated innate immune responses in hNS/PCs could ameliorate neurogenesis reduction." (PMID 33657175, 2021). "Interestingly, we found that ZIKV infection only reduced the protein level of Jak1 but not STAT1, while it had little effect on the mRNA level of Jak1." (PMID 28373913, 2017). "By immunoblot, the protein levels of STAT1 in ATF3 KO cells, without and with ZIKV infection, were notably decreased compared to WT cells." (PMID 39212382, 2024). "Following ZIKV infection, CD24-low and -high cells showed no significant change in total STAT1 levels or STAT1 phosphorylation detected by Western blotting (comparing lanes 1 to 2 and lanes 3 to 4) or by immunofluorescence." (PMID 36016357, 2022). "We further found that ZIKV infection in MDMs did not efficiently suppress type I IFN-mediated antiviral responses and failed to inhibit IFN-α-induced STAT1 and STAT2 phosphorylation." (PMID 33979266, 2021). "Our data further illustrated that ZIKV infection in MDMs did not efficiently suppress type I IFN-mediated antiviral response and failed to antagonize STAT1 and STAT2 phosphorylation induced by IFN-α treatment." (PMID 33979266, 2021). "We found that OAS2 overexpression activated the Jak/STAT signaling as shown by the increased level of p-STAT1, enhanced ISRE activity and up-regulated expression of several ISGs in A549 cells with and without ZIKV infection." (PMID 32276512, 2020). "Thus, to identify the mechanism by which NaAc, PBA, and NaB block the expression of these PRRs, cytokines, IFNs, and ISGs, we measured the activation of NFκB, MAPK (ERK1/2 and p38), STAT1, STAT2, and STAT3 signaling pathways in the presence and absence of these SCFAs following ZIKV infection." (PMID 41358724, 2026).
breast tumors (28 papers, 2007 to 2025). "STAT1 has long been implicated in growth suppression as loss of STAT1 function results in early development of breast tumours." (PMID 27769057, 2016). "Accordingly, studies with STAT1−/− mice show that the loss of STAT1 increases the incidence of breast tumors." (PMID 24810717, 2014). "However, the same authors demonstrated that the knock down of STAT1 induces luminal breast tumors in mice, which is correlated with the frequent loss of STAT1 in ERα-positive BC." (PMID 41463071, 2025). "In animal model, STAT1−/− may promote the spontaneous formation of breast tumors, with increasing susceptibility to tumorigensis initiated by ErbB2 and chemical carcinogenesis." (PMID 28422733, 2017). "Our study provided mechanistic insights and preclinical rationale for modulating the STAT1 regulon as a neoadjuvant regimen for MCT-primed breast tumors to achieve the maximum clinical benefit of the anti-PD1 immunotherapy." (PMID 37055410, 2023). "Here authors characterise the immune suppressive myeloid cells via single-cell analyses of immune cells from low dose chemotherapy treated breast tumours and identify STAT1 signalling as a regulator for immune suppressive state." (PMID 37055410, 2023). "The observation that the STAT1 levels in normal breast tissue was significantly higher than in matched breast tumor samples suggested that its expression was lost during tumor progression." (PMID 35681772, 2022). "A preponderance of in vivo data suggests that STAT1 acts as a tumor suppressor in preventing breast tumor initiation." (PMID 30150751, 2018). "To interrogate the functional significance of STAT1 in limiting the tumorigenic potential of breast tumours with low (MT/Shc2F/2F) versus high (MT/ShcA+/+; MT/Shc313F/313F) STAT3 activity, we deleted STAT1 by CRISPR/Cas9 genomic editing." (PMID 28276425, 2017). "Increased STAT1 activity in breast tumours promotes immune suppression by mobilizing myeloid-derived suppressor cells in human breast cancers." (PMID 28276425, 2017). "Evidence has correlated up-regulation of STAT1 activity with increased breast tumor progression and immune suppression in tumor microenvironment, thus STAT1 inhibition is a promising immune therapeutic target." (PMID 24550933, 2014). "MDA-231 breast tumor cells exposed to IFN-γ or IL-13 induced phosphorylation of STAT1 and STAT6, respectively." (PMID 24911872, 2014). "For example, SIAH2 expression correlates with breast tumor progression and malignancy and STAT1 exerts growth-inhibitory properties preventing mammary carcinogenesis in mice." (PMID 24833526, 2014). "A subset of the genes, such as Stat1 and Gbp4, were also up-regulated in adenoma tumors, suggesting that elements of the pathway were active in early breast tumors." (PMID 23520493, 2013). "This resulted in an overall higher STAT1 score in normal epithelial cells than in breast tumor cells." (PMID 22264274, 2012). "The relationship between overexpression of the IFN/STAT1 pathway and malignancy was initially described for breast tumors." (PMID 19503789, 2009). "Consistent with this notion, tyrosine phosphorylation of Stat1 was shown to be a marker in the prognostic evaluation of breast tumors as well as of head and neck tumors." (PMID 18941537, 2008). "Consistent with the variation we found in interferon-response gene expression in breast tumors, we found a large variability in the expression of STAT1 protein, the principal transcriptional regulator of the interferon response genes, in these tumors." (PMID 17868458, 2007). "We now show that STAT1 also perturbs the antioxidant defense mechanisms in breast tumors." (PMID 34083537, 2021). "We next interrogated whether our gene signatures could stratify STAT1 or STAT3 transcriptional responses in human breast tumours." (PMID 28276425, 2017).